S100A10 (S100 calcium binding protein A10)
Diseases named in the same sentence as S100A10 in open-access papers (continued):
Sharing a sentence is not in itself a finding about the gene and the disease.
serous ovarian cancer (5 papers, 2018 to 2021). "S100A10 was first identified and validated as a biomarker in an 11-member chemoresistance gene signature associated with poor overall survival in serous ovarian cancer patients treated with carboplatin and paclitaxel." (PMID 34944416, 2021). "They showed that high mRNA levels of S100A10 predict reduced OS and that high cytoplasmic S100A10 expression is significantly associated with reduced OS in serous ovarian cancer patients." (PMID 30572596, 2018). "Our findings support these observations and suggest that ATRA acts predominately on S100A10 in the plasminogen activation pathway in serous ovarian cancer cells." (PMID 30621740, 2019). "Current studies in our laboratory are investigating the ability of S100A10 antibodies to block serous ovarian cancer motility and invasion." (PMID 30572596, 2018). "Ongoing studies in our laboratory are investigating the ability of ATRA to inhibit cell proliferation and S100A10 expression in a range of serous ovarian cancer cell lines and serous ovarian cancer tissues using an ex-vivo explant assay." (PMID 30572596, 2018). "Together these findings suggest that S100A10 plays an important role in the progression of serous ovarian cancer and chemotherapy resistance." (PMID 30572596, 2018). "S100A4, S100B, S100A14, S100P expressions are associated with poor prognosis, moreover,high cytoplasmic S100A10 staining is significantly associated with reduced overall survival (OS) and progression-free survival (PFS) in serous ovarian cancer." (PMID 30558666, 2018). "ATRA (1 μM) also significantly decreased proliferation (Ki67 positivity, p = 0.0034), S100A10 protein levels (p = 0.0273), and increased cell apoptosis (cleaved caspase-3 positivity, p = 0.0024) in serous ovarian cancer tissues using the ex vivo tissue explant assay." (PMID 30621740, 2019). "Recent studies have linked S100A10 with chemotherapy resistance and poor prognosis in serous ovarian cancer; however, no functional studies have been performed to date." (PMID 30572596, 2018). "High S100A10 mRNA and protein expression also predicted poorer OS in serous ovarian carcinoma." (PMID 30009399, 2018). "In this study we determined the effects of ATRA treatment (1-5 μM) on annexin A2 and S100A10 expression, plasmin activation, and the ability of ATRA to inhibit serous ovarian cancer cell survival, motility and invasion in vitro." (PMID 30621740, 2019). "This study evaluated the effects of ATRA on annexin A2 and S100A10 expression, plasmin activation, and the ability of ATRA to inhibit serous ovarian cancer cell survival and invasion." (PMID 30621740, 2019).
anaplastic thyroid carcinoma (4 papers, 2018 to 2021). "It has been also reported that S100A10 expression contributed to the aggressive characteristics of thyroid anaplastic carcinoma." (PMID 30558666, 2018). "However, increased levels of S100A10 are present in all anaplastic thyroid carcinomas, which is the most aggressive form of thyroid malignancy, suggesting that S100A10 plays a role in the progression of thyroid carcinomas." (PMID 30572596, 2018).
brain tumor (4 papers, 2008 to 2022). "Overall, S100A10 had the highest fold change between ependymoma and other brain tumours of three and S100A4 had the highest fold change between ependymoma and normal brain of 20.7." (PMID 18781180, 2008). "However, investigations of the role of S100A10 in brain tumor immunity are scarce." (PMID 34148033, 2021). "S100A10 and S100A6 showed the highest mean expression across the six brain tumour types of 43.6 and 41.7 tags, respectively." (PMID 18781180, 2008). "Importantly, S100A10 expression was highly up-regulated in GB clinical samples as compared to non-neoplastic brain tumor, and higher expression of S100A10 was observed in both GB hypoxic core region and invasive margin compared to normal brain tissue." (PMID 32867190, 2020).
Cerebral ischemia (4 papers, 2023 to 2025). Restriction of arterial blood supply to the brain associated with insufficient oxygenation to support the metabolic requirements of the tissue. "Increased S100a10 expression, a hallmark of A2 astrocytes, has shown protective effects in cerebral ischemia-reperfusion injury." (PMID 40529227, 2025). "In cerebral ischemia, neuron- or astrocyte-derived 17β-estradiol regulates neuroprotective astrocyte activation and upregulates S100A10 following brain injury." (PMID 37759539, 2023).
colon cancer (4 papers, 2011 to 2018). "We found that calcitriol treatment in both right-sided and left-sided colon cancer causes a downregulation of ribosomal protein L37 and protein S100A10." (PMID 29324674, 2018). "Down-regulation of S100A10 in human macrophages inhibits the plasmin-induced release of pro-inflammatory cytokines such as interleukin-6, which has been suggested to promote cell growth and apoptosis-escape of colon cancer." (PMID 22206547, 2011). "S100A10 may be involved in releasing pro-inflammatory cytokines, such as interleukin-6, which has been suggested to promote cell growth and apoptosis-escape in colon cancer." (PMID 24851084, 2014). "Notably, we observed that PXR controls the expression of genes that were previously reported to confer CSC chemoresistance or to have a negative impact on disease-free survival in colon cancer patients, including ABCG2, ABCC6, ALDH1A1, CYP3A4, or S100A10." (PMID 27448961, 2016).
Hepatic steatosis (4 papers, 2017 to 2025). Steatosis is a term used to denote lipid accumulation within hepatocytes. "Hepatotropic AAV8 encoding shRNAs targeting S100A10 or S100A11 were used to downregulate these proteins specifically in the liver of mice fed a diet inducing hepatic steatosis, inflammation, and fibrosis and in a genetic mouse model of MASLD bearing hepatocyte-specific deletion of PTEN (LPTENKO)." (PMID 40841353, 2025). "We tested the function of an upregulated LDP, S100a10, in vivo with adenovirus-mediated gene silencing and found, unexpectedly, that knockdown of S100a10 accelerated progression of HFD-induced liver steatosis." (PMID 28179399, 2017). "We tested the function of an upregulated LDP, S100a10, in HFD liver and found, unexpectedly, that S100a10 knockdown accelerated progression of HFD-induced liver steatosis." (PMID 28179399, 2017). "Label-free quantification for S100a10 also demonstrated its upregulation in the LDP of HFD-induced fatty liver in mice." (PMID 28179399, 2017). "As the S100a10 level was elevated in HFD-fed mice, we expected that its loss would result in a slowdown of liver steatosis progression." (PMID 28179399, 2017). "Although not displaying hepatic steatosis, the tumors developing in this setting are known to be lipophagic, which could be relevant for the protective effects of S100A10." (PMID 40841353, 2025).
medulloblastoma (4 papers, 2007 to 2021). A malignant, invasive embryonal neoplasm arising from the cerebellum. "For example, DNA hypomethylation resulted in reduced S100A6 and S100A10 expression in medulloblastoma while somatic methylation controlled S100A2 and S100A4 expression in the normal cerebellum, showing tissue specific regulation." (PMID 34485305, 2021). "This study demonstrates a role for the epigenetic deregulation of three members of the S100 gene family, S100A4, S100A6 and S100A10, in medulloblastoma tumourigenesis." (PMID 17579622, 2007). "Two of the genes identified by this approach, S100A6 and S100A10, were each hypermethylated in a proportion of both medulloblastoma cell lines and primary tumours (each in ∼12% of cases), but not in the normal cerebellum." (PMID 17579622, 2007). "However, S100A10 can interact with a variety of proteins and is involved in diverse processes, and studies to clarify its role in medulloblastoma tumourigenesis are now required." (PMID 17579622, 2007). "The expressions of S100A1, S100A4, S100A10, and S100A11 are regulated by DNA methylation in medulloblastoma and may have potential impacts on the disorder of telencephalon in cerebral hernia." (PMID 32867218, 2020). "Assessment of these genes in the non-neoplastic cerebellum (from which medulloblastomas develop) revealed strong somatic methylation affecting S100A2 and S100A4, whereas S100A6 and S100A10 were unmethylated." (PMID 17579622, 2007).
non-small cell lung carcinoma (4 papers, 2011 to 2021). A group of at least three distinct histological types of lung cancer, including non-small cell squamous cell carcinoma, adenocarcinoma, and large cell carcinoma. "For example, high levels of two S100 proteins, i.e., S100A10 and S100A16, are associated with non-small cell lung cancer (Uhlenet al., 2017)." (PMID 29904729, 2018).
pancreatitis (4 papers, 2016 to 2022). Inflammation of the pancreas. "Pancreatitis samples were also examined and had similar levels of S100A10 compared to normal epithelium." (PMID 34944416, 2021). "Additionally, in Logsdon’s datasets, S100A10/A11 were overexpressed in pancreatic adenocarcinoma (fold change = 7.58 and 18.29), and pancreatitis (fold change = 2.97 and 5.45) compared to normal samples." (PMID 34804125, 2021).
Anxiety (3 papers, 2020 to 2025). Intense feelings of nervousness, tension, or panic often arise in response to interpersonal stresses. "Together, these results indicate that the anxiety phenotype of Sh + Flx animals is not due to the molecular adaptations in the layer 5a S100a10 neurons but likely a result of Flx-dependent changes occurring in other cell-types or brain regions." (PMID 31431686, 2020).
atherosclerosis (3 papers, 2021 to 2024). A disease characterized by the build-up of fatty material and calcium deposition in the arterial wall resulting in partial or complete occlusion of the arterial lumen. "Increased expression of S100A10 is associated with thrombosis and atherosclerosis." (PMID 38474140, 2024). "Three pivotal atherosclerosis-associated genes—CD36, S100A10, CSNK1A1—were unveiled, offering valuable clinical insights." (PMID 39660117, 2024). "The entire process harnessed multiple machine learning algorithms to elucidate the fundamental signature genes intrinsic to atherosclerosis, ultimately pinpointing CD36, S100A10, and CSNK1A1 as genetically correlated markers." (PMID 39660117, 2024). "In summary, our study highlights monocyte infiltration as a crucial contributor to atherosclerosis development, with CD36, S100A10, and CSNK1A1 emerging as prominent biomarkers for disease detection." (PMID 39660117, 2024). "Implications of S100A10 and S100A12 in atherosclerosis could entail differences in their expression in LEAD and CVD groups, however acetylic acid medication could also be causative for obtained results." (PMID 33801150, 2021). "Moreover, ssGSEA analysis of model genes in the marker gene set of the GSEA database revealed that CD36 and S100A10's activities in the respective marker gene sets were precisely opposite to CSNK1A1, highlighting distinct regulatory roles of these genes in the context of atherosclerosis." (PMID 39660117, 2024).
coronary artery disease (3 papers, 2015 to 2025). "For example, rs3184504, a nonsynonymous SNP in SH2B3 that was associated in GWAS with BP, coronary heart disease, hypothyroidism, rheumatoid arthritis, and type 1 diabetes, is a trans-eQTL for 6 of our 34 BP signature genes from the meta-analysis (FOS, MYADM, PP1R15A, TAGAP, S100A10, and FGBP2)." (PMID 25785607, 2015). "At present, there is a lack of evidence on the role of S100A10 in ischemic heart disease." (PMID 41195005, 2025).
ischemic stroke (3 papers, 2023 to 2024). A stroke disorder caused by obstruction of blood flow to the brain, due to thrombotic (local blood clot formation) or embolic (due to a blood clot or other material traveling from another site) event. "A previous study reported that neuroinflammation induced C3-positive reactive astrocytes and ischemic stroke activated S100A10-positive reactive astrocytes." (PMID 38188669, 2023).
liver disease (3 papers, 2017 to 2025). "Therefore, we hypothesize that S100A10 protects against liver tumor incidence specifically in a context of steatotic liver disease (LPTENKO and HFD-DEN) or in lipophagic, less aggressive tumors (mutated β-catenin tumors) representing by itself around 30% of HCC patients." (PMID 40841353, 2025). "In this context, we aimed to assess the therapeutic potential of targeting hepatocyte S100A10 and S100A11 in liver disorders." (PMID 40841353, 2025). "The different mouse models with various etiologies could collectively recapitulate the human disease and shed new light on the roles of S100A10 and S100A11 in liver diseases." (PMID 40841353, 2025). "Moreover, S100A10 was found to be unregulated in HCC patients and positively correlated with tumor progression, suggesting a close relationship between S100A10 and liver disease." (PMID 28179399, 2017).
papillary thyroid cancer (3 papers, 2021 to 2026). "Using S100A10 as a distinct biomarker for papillary and anaplastic carcinoma would help detect these cancers in earlier stages and dramatically improve prognosis by preventing the transformation of papillary carcinoma to anaplastic carcinoma." (PMID 34944416, 2021). "It is also important to note that S100A10 expression did not increase with cancer progression for papillary carcinoma." (PMID 34944416, 2021).
Salmonella Infections (3 papers, 2023 to 2025). Infections with bacteria of the genus SALMONELLA. "While, KEGG analysis showed that S100A10 was involved in complement and coagulation cascades and salmonella infection." (PMID 37420211, 2023). "CASP14 and S100A10 are involved in Salmonella infection (P = 0.2076)." (PMID 40029616, 2025).
steatosis (3 papers, 2022 to 2025). Increased lipid within the cytoplasm of cells. "Next, we tested short-term/acute intervention on S100A10 or S100A11 for potential beneficial effects on steatosis reduction in an early phase by downregulating for only 1 month either S100A10 or S100A11 at 4 months of age." (PMID 40841353, 2025). "Downregulation of S100A10 promoted hepatocarcinogenesis in a fatty liver setting, while reducing steatosis and fibrosis development." (PMID 40841353, 2025). "After 10 weeks of FPC diet, S100A10 or S100A11 knock-down reduced steatosis development, assessed by the measurement of liver triglyceride content and by automatic quantification of lipid droplets density on H&E coloration." (PMID 40841353, 2025). "Translated at the clinical level, one can hypothesize that activation of S100A10 in patients presenting steatosis might dampen cancer initiation/progression." (PMID 40841353, 2025). "Whether this effect is a consequence of an improvement of steatosis or a direct contribution of S100A10 on stellate cells activation remains to be established." (PMID 40841353, 2025). "Indeed, targeting S100A10 with AAV-based strategy reduced the extent of steatosis and fibrosis." (PMID 40841353, 2025). "From 6 to 11 months of age, after steatosis development, LPTENKO mice were subjected to AAV8-based S100A10 or S100A11 downregulation." (PMID 40841353, 2025).
anaplastic carcinoma (2 papers, 2008 to 2021). "In contrast, all papillary and anaplastic carcinoma samples stained positively for S100A10, with significantly higher expression in anaplastic carcinoma." (PMID 34944416, 2021). "More recently it has been shown by IHC analysis that S100A10 expression in thyroid neoplasms contributes to the aggressive characteristic of anaplastic carcinoma." (PMID 18827820, 2008). "Therefore, S100A10 can detect papillary at an early stage of development, and treatment can prevent further progression into anaplastic carcinoma, an aggressive and highly metastatic cancer." (PMID 34944416, 2021).
Barrett adenocarcinoma (2 papers, 2017 to 2021). An adenocarcinoma arising from Barrett metaplastic epithelium in the esophagus. "Diseases associated with S100A10 include Trachea Leiomyoma and Barrett’s Adenocarcinoma." (PMID 34530774, 2021).
brain cancer (2 papers, 2020 to 2021). A primary or metastatic malignant neoplasm affecting the brain. "Although there are few studies investigating S100A10 in brain cancers, this paper shows a new and promising potential of S100A10 expression as a biomarker, predictor of prognosis, and therapeutic target in LGG." (PMID 34944416, 2021).
breast tumor (2 papers, 2020 to 2021). "In this study, we investigated the role of protein S100A10 (p11) in breast tumor growth, progression, and metastasis using mouse cancer models and patient tumor sample analysis." (PMID 33297495, 2020). "Therefore, future studies should evaluate the expression of S100A10 protein in a large cohort of breast tumor tissues to validate these preliminary findings." (PMID 34944416, 2021). "For example, we observed increased expression of S100A10 mRNA and protein in high-grade tumors, estrogen receptor (ER+) positive, human epidermal growth factor receptor 2 (HER2)-enriched breast tumors, and triple-negative (TN) compared to normal breast tissues." (PMID 34944416, 2021).
cardiomyopathy (2 papers, 2024 to 2025). A disease of the heart muscle or myocardium proper. "Notably, CD36 and S100A10 displayed negative correlations in Vascular smooth muscle contraction, Basal cell carcinoma, and different types of cardiomyopathy, and positive correlations in Allograft rejection and Asthma, among others." (PMID 39660117, 2024).
epilepsy (2 papers, 2022 to 2024). A brain disorder characterized by episodes of abnormally increased neuronal discharge resulting in transient episodes of sensory or motor neurological dysfunction, or psychic dysfunction. "The neuroprotective role of S100A10 in epilepsy may be related, in particular, to its effect on the serotoninergic system, which plays a protective role in epileptogenesis." (PMID 39337503, 2024).
gallbladder cancer (2 papers, 2021 to 2022). "High expression levels of S100A10 were significant in later stages of gallbladder cancer, positive lymph node metastasis, and short survival." (PMID 34944416, 2021). "Therefore, the expression of S100A10 is exclusive to gallbladder cancer and holds great potential as a biomarker for the early detection of gallbladder cancer." (PMID 34944416, 2021). "Moreover, 90% of the gallbladder cancer samples stained positive for S100A10." (PMID 34944416, 2021).
gastric tumors (2 papers, 2019 to 2021). "Results from Oncomine, GEPIA, UALCAN, and TCGA databases confirmed the presence of high S100A10 expression in gastric tumors compared to normal mucosa." (PMID 34944416, 2021). "S100A10 was immunoprecipitated from seven gastric tumors and their adjacent normal mucosa to see whether levels of lysine succinylation were present in either of these groups." (PMID 34944416, 2021). "We immunoprecipitated S100A10 from a panel of seven pairs of primary gastric tumours and their adjacent normal tissues to investigate whether this modification was present." (PMID 30394687, 2019).
Hepatic fibrosis (2 papers, 2023 to 2026). The presence of excessive fibrous connective tissue in the liver. "Our previous work identified S100A10 as a MASLD promoter, suggesting that its association with AnnexinA2 (ANXA2) within the S100A10-ANXA2 heterotetramer (A2t) might promote hepatic fibrosis." (PMID 42271090, 2026). "By stimulating proinflammatory cascades by inflammatory gene expressing and profibrogenic cytokine releasing including Il1b, Tnf, Lgals3, S100a6, S100a4, S100a11, and S100a10, Mac1 was characterized as one of the profibrotic contributors during the liver fibrosis progression." (PMID 37724132, 2023).
Human Papillomavirus Infection (2 papers, 2012 to 2022). "The S100A10 subunit promotes L2-mediated human papillomavirus infection, which is associated with the development of CESC." (PMID 36685937, 2022).